RNU6-545P (RNA, U6 small nuclear 545, pseudogene)
Synonyms: RNU6-292P
Gene: Small nuclear RNA gene on chromosome 12 (12,226,674 to 12,226,777, forward strand). Ensembl gene ENSG00000199551.
Homologues: Orthologues: chimpanzee U6 (100% identical), macaque U6 (79% identical), guinea pig U6 (69% identical). Paralogues in human: RNU6-25P (83% identical), RNU6-33P (83% identical), RNU6-38P (83% identical), RNU6-476P (83% identical), RNU6-574P (83% identical), RNU6-1 (82% identical), RNU6-1011P (82% identical), RNU6-11P (82% identical), RNU6-132P (82% identical), RNU6-140P (82% identical), RNU6-15P (82% identical), RNU6-2 (82% identical), and 1284 more.